JAK1 (Janus kinase 1)
Diseases named in the same sentence as JAK1 in open-access papers (continued):
Sharing a sentence is not in itself a finding about the gene and the disease.
hepatocellular carcinoma (36 papers, 2013 to 2026). A malignant tumor that arises from hepatocytes. "JAK1 mutations are found in varying types of cancers; e.g., 9% of hepatocellular carcinoma patients have been found to have JAK1 mutations." (PMID 31892268, 2019). "Similarly, JAK1 mutations were found in 9% cases of hepatocellular carcinoma; in particular, the S703I mutation is likely responsible for the loss of JAK1 auto-inhibition ability." (PMID 32707925, 2020). "JAK1 mutations have been identified in hepatocellular carcinoma (HCC) patient tumors; patient-derived xenografts with JAK1 S703I mutations had elevated levels of phosphorylated STAT3 and STAT5." (PMID 33521321, 2020). "This aligns with Bacteroides‐derived acetate activating JAK1/STAT3 to promote M1 polarisation in hepatocellular carcinoma, indicating a conserved immunometabolic axis." (PMID 40739711, 2025). "For those of normal weight, the hepatitis B pathway, composed of RB1, EP300, PIK3CB, HSPG2 and JAK1 (K = 9), may serve as a key point for effective treatment and prevention, because chronic infection with hepatitis viruses is a major causative factor for hepatocellular carcinoma." (PMID 40768543, 2025). "The M2 macrophages are abundant in hepatocellular carcinoma tumors, and correlate with the activation of the JAK1/STAT6 signaling pathway." (PMID 35269804, 2022). "MicroRNA-340 inhibits the proliferation and invasion of Hepatocellular Carcinoma cells by targeting JAK1." (PMID 33193744, 2020). "JAK1 promotes hepatoma cell migration in an ACAP4-ARF6-dependent manner in response to IL6." (PMID 39744421, 2025). "Similarly, NC suppressed the Janus kinase 1 (JAK1)/STAT3 pathway and caused cell growth inhibition in hepatocellular carcinoma." (PMID 33288736, 2020). "JAK1 activation phosphorylates ACAP4 at Tyr843, thereby increasing ARF6-GTPase activity to promote hepatoma cell migration and HCC metastasis." (PMID 39744421, 2025). "During IL6-induced JAK1 signaling in tumor cells, we identified a novel phosphorylation site of ACAP4 at Tyr843 that facilitates hepatoma cell migration by increasing ARF6-GTPase activity." (PMID 39744421, 2025). "Liver KCs are polarized to TAMs by the induction of hepatoma cell-derived exosomes, which then secrete IL6 and activate JAK1 in hepatoma cells." (PMID 39744421, 2025). "In hepatocellular carcinoma (HCC), IL- 6 activates JAK1/PD-L1 phosphorylation at the Y112 site, followed by stimulation of STT3A recruitment and subsequent glycosylation to increase PD-L1 expression." (PMID 37554324, 2023). "More recently, IL-6/JAK1-mediated STAT3 phosphorylation was found to promote the transcription of DNMT3B and OCT4 in hepatocellular carcinoma cells, which can further up-regulate the transcription of DNMT156." (PMID 32895373, 2020). "For instance, NC was reported to suppress cell growth via inhibition of the Janus kinase 1 (JAK1)-STAT3 (signal transducer and activator of transcription 3)-signaling pathway in hepatocellular carcinoma." (PMID 30847386, 2019). "In addition, consistent with our results, Bifidobacterium pseudolongum-generated acetate reached the liver via the portal vein, where it suppressed the IL-6/JAK1/STAT3 signaling pathway in hepatocytes, thereby preventing hepatocellular carcinoma." (PMID 40693815, 2025). "IL6 then activates JAK1 to phosphorylate its downstream effector ACAP4 at Tyr843, a novel phosphorylation site identified in this context, which in turn promotes ARF6-GTPase activity and hepatoma cell migration." (PMID 39744421, 2025). "In vitro studies demonstrated that AZD1480, an ATP-competitive inhibitor of JAK1 (Janus kinase 1) and JAK2 (Janus kinase 2), could inhibit HAV genotype III replication in human hepatoma cells." (PMID 37243166, 2023). "Suppression of IL6/JAK1-mediated PD-L1 glycosylation sensitized anti-Tim3 immune checkpoint blockade (ICB) therapy as manifested by reduced tumor growth and prolonged survival in Hepa1-6 hepatoma-bearing mice." (PMID 37193819, 2023).
hepatocellular carcinoma (continued). "Furthermore, IL4R plays an essential role in regulating hepatocellular carcinoma (HCC) cell survival, proliferation, and metastasis and regulates the activation of JAK1/STAT6 and Jnk/Erk1/2 pathways." (PMID 31540495, 2019). "In addition to JAK-1, IL-6/JAK-2/STAT3 activation and tumor progression in hepatocellular carcinoma has recently been reported." (PMID 23555719, 2013). "By investigating the impact of vitexin on the STAT3 signaling pathway and key cancer markers, researchers have demonstrated that vitexin can successfully disrupt the sustained activation of JAK1, JAK2, and STAT3 in hepatocellular carcinoma (HCC) cells." (PMID 38915462, 2024). "In hepatocellular carcinoma (HCC), miR-340 inhibits cell proliferation and tumor growth by inhibiting SKP2 expression 47, and regulating the JAK1/STAT3 pathway." (PMID 33390846, 2021).
leukemia (36 papers, 2012 to 2026). A malignant (clonal) hematologic disorder, involving hematopoietic stem cells and characterized by the presence of primitive or atypical myeloid or lymphoid cells in the bone marrow and the blood. "Mutations in JAK1 are less common than in T-ALL patients with B-ALL or leukemia of the myeloid origin." (PMID 35529449, 2022). "This study discovered and characterized a Jak1 Y1034C mutation found in a naturally occurring F344 rat NK-LGL leukemia model." (PMID 31947841, 2020). "Several JAK1 mutations were found in different cancer types, such as leukemia, breast cancer, lung cancer, and HCC." (PMID 26701727, 2016). "Furthermore, STAT3β-deficient leukemia cells were specifically vulnerable to interference with IFN signaling through the JAK1/2 inhibitor Ruxolitinib." (PMID 38806478, 2024). "Importantly, we demonstrate a leukemia-associated JAK1 mutation overrides the palmitoylation-dependence of JAK1 activity, potentially explaining why this mutation is oncogenic." (PMID 37356718, 2023). "We also asked whether JAK1 V658F mutation, which was identified in cases of leukemia and is reported to increase JAK1 activity in cells, can overcome the requirement for palmitoylation." (PMID 37356718, 2023). "Interestingly, this requirement for palmitoylation cannot be overcome by a heterologous lipid modification but is overridden by a well-known leukemia-associated JAK1 mutation." (PMID 37356718, 2023). "JAK1 mutations in B-ALL or leukemia of the myeloid origin are rarer than in T-ALL." (PMID 33672930, 2021). "Overall, one of the concerns was the loss of a graft-vs.-leukemia effect, given the pharmacological interference with the JAK1/2 signal pathway; however, the reported rate of disease recurrence after Ruxolitinib was of 9.3 and 2.4 % of the patients in the aGVHD and cGVHD groups, respectively." (PMID 27502249, 2016). "Moreover, an activating Jak1 p.F837V variant was identified in one of the leukemic samples, which again highlights the importance of the JAK/STAT-signaling pathway in Pax5+/− leukemias, as shown for Jak1 and Jak3 mutations in the Pax5+/− delayed-exposure B-ALL3,25." (PMID 37620322, 2023). "Additionally, RNK-16 engraftment represents an in vivo model of a leukemia driven by mutationally activated JAK1, which may have utility for the evaluation and development of JAK1 inhibitors." (PMID 31947841, 2020). "Accordingly, STAT3β-deficient leukemia cells displayed enhanced sensitivity to blockade of IFN signaling through both an IFNAR1 blocking antibody and the JAK1/2 inhibitor Ruxolitinib." (PMID 38806478, 2024). "Janus Kinase-1 (JAK1) plays key roles during neurodevelopment and following neuronal injury, while activatory JAK1 mutations are linked to leukemia." (PMID 37356718, 2023). "The JAK pseudokinase homologs JAK2 R683G and JAK1 R724H appear to reside within an important area as more than one alteration of these residues is related to leukemia, R683S/G, and R724H/Q/S." (PMID 37834019, 2023). "Adopting the SWISS-MODEL structures, many of the JAK1 and JAK3 leukemia-driving variants are located within dynamic regions including small loops." (PMID 37834019, 2023). "In two AML patients, a JAK1 mutation V623A was found, emphasizing the capacity of constitutively active JAK1 to induce a variety of leukemias." (PMID 35529449, 2022). "As JAK3 mutants are dependent on JAK1 signaling for their cellular transformation, it is possible to use both JAK1/JAK2 and JAK3‐selective inhibitors in JAK3 mutation–positive leukemia." (PMID 35846099, 2021). "Similar to JAK1 and JAK2 mutations, the most prevalent mutations in JAK3: M511I, A573V, and R657Q can drive several types of leukemia." (PMID 33672930, 2021).
leukemia (continued). "Different types of leukemia harbor genomic aberrations in all four JAKs (JAK1, JAK2, JAK3, and TYK2), most of which are activating somatic mutations and less frequently translocations resulting in constitutively active JAK fusion proteins." (PMID 33672930, 2021). "All NOTCH1-signaling-dependent T-ALL cell lines were sensitive to MRK-560 and its combination with ruxolitinib or imatinib in JAK1- or ABL1-dependent cell lines synergistically inhibited leukemia proliferation." (PMID 34167562, 2021). "JAK1 is associated with IL-7Rα, leading us to evaluate efficacy of ruxolitinib, a potent JAK1 inhibitor in a leukemia model driven by mutant IL-7Rα." (PMID 29854301, 2018). "JAK1/2 inhibitor inactivated the mTOR/p70S6K/4EBP1 pathway and reduced the inhibitory phosphorylation of GSK3 in leukemia cell line, which correlated with JAK1/2 inhibitor reduction of proliferation and survival of these cells." (PMID 26275051, 2015). "Due to the molecular heterogeneity in AML, genetic abnormalities can vary between individual cases of leukemia, and there may be rare cases where JAK1, PDGFRA and FGFR2 abnormalities are present in CBF-AML." (PMID 37509244, 2023). "However, a JAK1 V623A mutation was detected in two AML patients, highlighting the ability of constitutively active JAK1 to drive various types of leukemia." (PMID 33672930, 2021). "JAK1V658F was found in leukemia patients, leading to constitutional activation of JAK1." (PMID 26701727, 2016). "In the current study, we further demonstrate and confirm that the pharmacologic inhibition of JAK1/JAK2 preserves the beneficial anti-leukemia effect previously reported by our group in IFNγR−/− T cells in two different leukemia models (A20 lymphoid leukemia and APL myeloid leukemia)." (PMID 25289677, 2014). "From RPPA data we performed a hierarchical cluster analysis considering the JAK1/2-STAT6 pathway in T-LBL cases based on good and poor prognosis and 13 commercially available leukemia cell lines." (PMID 34359628, 2021). "It will be of interest to investigate both JAK1 and JAK3 kinase inhibitors as targeted agents for these leukemias." (PMID 26208852, 2015). "ROCK1/2 inhibition improved survival and histological GVHD severity in mice and was synergistic with JAK1/2 inhibition, without compromising graft-versus-leukemia-effects." (PMID 38199985, 2024). "Of note, ALL-SIL, MOLT-4 and RPMI-8402 cell lines showed a JAK1/2-STAT6 activation profile close to patients with worse prognosis as well as high levels of JAK2 Y1007-1008 compared to good prognosis patients and to the other leukemia cell lines." (PMID 34359628, 2021). "Considering the crucial role of JAKs in the development and function of hematopoietic cells, it is not surprising that JAK1, JAK2, and JAK3 mutations are often found in leukemia." (PMID 33672930, 2021). "We treated these leukemias with the combination of DEX and inhibitors of JAK1/2 (ruxolitinib), MEK (trametinib), or Akt (MK2206) at concentrations that attenuated TSLP-induced signaling in the CRLF2R Ph-like ALL cell line Mutz-5 and that did not demonstrate toxicity in healthy PBMCs." (PMID 31318944, 2019). "In our animal studies, JAK1/2 inhibitor Ruxolitinib alone improved the survival in mice bearing T315I leukemia compared to the group treated with Dasatinib but not to a significant extent." (PMID 27551334, 2016). "By targeting both JAK1 and JAK3 in JAK3 mutant leukemia cells, it may be very difficult for the leukemia cells to overcome this block by just one mutation." (PMID 26208852, 2015). "The authors demonstrated the synergistic activity of JAK1 inhibition and ATRA in non-APL leukemia." (PMID 41590345, 2026).
prostate carcinoma (35 papers, 2007 to 2025). A carcinoma that arises from epithelial cells of the prostate gland. "From these data, we conclude the growth inhibitory effect of RBN2397 in prostate cancer cells is separable from its effects on IFN signaling that are linked to the kinase activities of JAK1/2 and TBK1." (PMID 37077937, 2023). "Data from TGCA sustain that MSI tumors (endometrial, colorectal, stomach, and prostate carcinoma) have recurrent frameshift mutations in JAK1, and these tumors showed reduced expression of interferon response signature." (PMID 34072037, 2021). "In another study, thirty-seven patients with microsatellite unstable prostate cancer were analyzed, and JAK1 mutations were present in 68% of them." (PMID 34072037, 2021). "Due to the central role played by JAK1 in IFN signaling, we first evaluated the prevalence of JAK1 mutations in prostate cancer by accessing the cBioPortal database." (PMID 27366948, 2016). "The LNCaP cell line is an altered prostate cancer cell line deficient of JAK1, a key component in the JAK/STAT pathway." (PMID 26452032, 2015). "Furthermore, poly I:C/IFN γ at the concentration we used was unable to induce apoptosis in LNCaP cells, an altered prostate cancer cell line deficient of JAK1." (PMID 26452032, 2015). "Additional research suggests Ganoderma lucidum’s capacity to inhibit prostate cancer cell development and induce apoptosis through the Jak-1/STAT-3 signaling pathway." (PMID 40141325, 2025). "Our collective research has also shown that CFF-1 exerts potent anti-tumor immunity, effectively hindering tumor growth and metastasis in prostate cancer via the EGFR/JAK1/STAT3 pathway, subsequently inhibiting PD-1/PD-L1 checkpoint signaling." (PMID 38484140, 2024). "The overexpression of IL-6 and JAK-1 is required for the STAT-3 activations that lead to prostate cancer proliferation and migrations." (PMID 39574470, 2024). "Intrigued by the nexus between cytokine signalling and transcriptional control, we postulate that the IL-11 autocrine loop is a determinant of docetaxel resistance in prostate cancer via the JAK1/STAT4 signalling axis." (PMID 38429845, 2024). "To this end, we employed specific inhibitors to TBK1 (GSK8612; GSK) and JAK1/2 (Ruxolitnib; Ruxo) in prostate cancer cell lines and induced PARP7 via AHR (PC3, DU145) and AR (PC3-AR)." (PMID 37077937, 2023). "As another example, lncAMPC activates LIF/LIFR/Jak1/STAT3 pathway to stable PD-L1 and metastasis-associated genes, thereby contributing to metastasis and immunosuppression in prostate cancer." (PMID 33665192, 2021). "3,3′,4,5′-THS was a Janus kinase inhibitor (JAK1), and it was reported to be cytotoxic against prostate cancer cells." (PMID 29109374, 2017). "Further classification of this cohort into prostate cancer subtypes, revealed that 90 % of the JAK1 deep deletions occurred in the ‘ERG fusion’ subtype (p = 4.542e−3)." (PMID 27366948, 2016). "Since epigenetic silencing of JAK1 was reported in prostate cancer cell lines, we next analyzed the extent of methylation of JAK1 in patient-derived samples of the TCGA cohort, and correlated this methylation with JAK1 expression levels." (PMID 27366948, 2016). "The potential to overcome resistance by inhibiting the IL-11/IL-11RA/JAK1/STAT4 axis may represent a paradigm shift in prostate cancer treatment." (PMID 38429845, 2024). "Finally, we used chemical inhibitors to TBK1 and JAK1/2 to show that RBN2397 inhibition of prostate cancer cell growth can be distinguished from the RBN2397 effect on PARP7 regulation of type I IFN signaling." (PMID 37077937, 2023). "MiR-583 inhibited prostate cancer cell proliferation and invasion by targeting JAK1." (PMID 38003649, 2023). "Moreover, miR-583 has been found to repress the proliferation and invasion of prostate cancer cells via modulating JAK1." (PMID 35602296, 2022).
prostate carcinoma (continued). "In conclusion, the combination therapy with JAK1 inhibitors and docetaxel could be a useful therapeutic strategy in the treatment of prostate cancers." (PMID 34322995, 2021). "RKIP overexpression in breast and prostate cancer cell lines was shown to inhibit cellular Src (c-Src) autophosphorylation and activation, as well as interleukin 6 (IL-6)-, janus kinase 1/2 (JAK1/2)-, and activated Raf-mediated STAT3 tyrosine and serine phosphorylation, needed for STAT3 activation." (PMID 30149591, 2018). "Thus, in normal growth conditions, the lack of expression of functional JAK1 in LNCaP cells should phenocopy prostate cancers with deep deletions in JAK1." (PMID 27366948, 2016). "One possible mode by which IL-6 may influence progression of prostate cancer to the hormone-refractory state is by activating the IL-6 receptor/JAK1/STAT3 pathway, resulting in differentiation and inhibition of apoptosis." (PMID 17595657, 2007). "CA treatment on IL-6, JAK1, and p-STAT-3 (tyr705) expression in prostate cancer cells PC-3 were examined by western blotting." (PMID 39574470, 2024). "Suppression of JAK1/2 by AZD1480 also inhibited progression of CRPC 37 and reduced IL6‐induced metastases, suggesting that JAK signalling is activated in prostate cancer." (PMID 34322995, 2021). "In a study of patients with prostate cancer, 1,25(OH)D was found to suppress many JAK-STAT signal components, including JAK1, STAT1, STAT2 and STAT3, which is consistent with our study." (PMID 32158346, 2020). "JAK1 led to STAT3 activation, which belonged to cytokine signal transduction pathway and found in prostate cancer." (PMID 29109374, 2017). "While previous research indicated that CDN selectively inhibits JAK2-but not JAK1-in prostate cancer models." (PMID 41585878, 2025). "Notably, upon neutralization of IL-11 signalling using an IL-11 antagonist, the expression and phosphorylation levels of JAK1 and STAT4 were markedly altered, substantiating the pivotal role of IL-11 in activation of the JAK/STAT pathway in prostate cancer." (PMID 38429845, 2024). "LIF significantly upregulates the phosphorylation of JAK1 and sustains JAK1/STAT3 signalling by binding to the receptor LIFR, strongly preventing the differentiation of HCC cells and promoting the metastasis and an immunosuppressive phenotype of prostate cancer." (PMID 36104718, 2022). "Agarwal and colleagues have also found that the combination of the Jak1 inhibitor and silibinin (an active constituent of silymarin) is able to reduce STAT3 phosphorylation and to activate caspase-9 and caspase-3, thus leading to the apoptosis of prostate cancer DU145 cells." (PMID 33299414, 2020). "Finally, we could not confirm the association of JAK1 frameshifts and MSI in prostate cancer since only 3 JAK1 frameshift mutations were detected out of 498 samples tested." (PMID 29121062, 2017). "Members of nonreceptor tyrosine kinase (NRTK) including Src, FAK, JaK1/2, and ETK were involved in the cell proliferation, migration, invasion, angiogenesis, and apoptosis of prostate cancer." (PMID 36095024, 2022).